EGFR (epidermal growth factor receptor)
Diseases named in the same sentence as EGFR in open-access papers (continued):
Sharing a sentence is not in itself a finding about the gene and the disease.
lung cancer (continued). "Sequential regimens in patients with epidermal growth factor receptor (EGFR) mutation-positive non–small cell lung cancer (NSCLC) can overcome tyrosine kinase inhibitor (TKI) resistance and maximize clinical benefit." (PMID 38204337, 2024). "EGFR mutations occurred less frequently in subpleural fibrotic ILA, a finding that corresponds to previous studies that reported a low prevalence of EGFR mutations in patients with lung cancer and UIP or IPF." (PMID 38783331, 2024). "The association between GERD and the risk of lung cancer with EGFR mutations in LCINS requires further research for confirmation." (PMID 39527539, 2024). "The most common mutation in NSCLC is an EGFR mutation, and there are significant regional differences in EGFR mutations in lung cancer patients." (PMID 39364008, 2024). "Detecting EGFR mutations in lung cancer using ctDNA allows for the assessment of various clinical information, such as the response to ositinib therapy, survival time, and the risk of distant metastasis in lung cancer." (PMID 38561776, 2024). "Patients with lung cancers harboring minor EGFR mutations showed a tendency of longer TTNT for ICIs (median 7.6 vs. 3.8 months, p = 0.133) than patients with major EGFR mutations." (PMID 38347279, 2024). "Common mutations included EGFR (29%), in 86 lung cancer patients, and PIK3CA (22%), identified in 13 breast cancer patients." (PMID 39061145, 2024). "In the tested lung cancer samples from Mexican patients, the mutation frequencies of EGFR and KRAS were 30 and 10%, respectively, while in Colombian patients, these frequencies were 23 and 13%." (PMID 38581481, 2024). "Next, we analyzed scRNA-seq data from patients with EGFR-mutated lung cancer before EGFR-TKI treatment and after the development of drug resistance to confirm results seen in cell lines and compare gene expression levels in tumor and non-tumor cells." (PMID 39122703, 2024). "Despite the significant disruption caused by EGFR mutations in lung cancer, their oncogenic consequences on transformed epithelial subpopulations still require investigation." (PMID 38546390, 2024). "Smoking can alter airway epithelial differentiation and barrier function by activating EGFR in airway basal cells, which is associated with development of smoking-associated lung cancers." (PMID 39720074, 2024). "Currently, the treatment of patients diagnosed with lung cancer who present sensitive EGFR mutations is basically defined by the result of mutation detection in tumor tissue biopsy or liquid biopsy in blood." (PMID 39421175, 2024). "This is consistent with Li’s research that patients with lung cancer with EGFR mutations are more likely to develop brain metastases than patients with EGFR wild-type (OR = 1.99, 95% CI: 1.59–2.48, P = 0.000)." (PMID 38605303, 2024). "Disruptions in downstream signalling, often due to EGFR mutations, are associated with the development of aggressive tumour traits, particularly seen in certain lung cancers." (PMID 38685671, 2024). "For instance, lung cancer cells with EGFR mutations that have metastasized to the brain can develop resistance to Osimertinib, a third-generation EGFR tyrosine kinase inhibitor (TKI), through the acquisition of an additional K-Ras G12V mutation." (PMID 39596025, 2024). "Mechanisms of resistance to targeted therapy: Epidermal growth factor receptor tyrosine kinase inhibitors (EGFR-TKIs), which target early-stage lung cancer with EGFR mutations, have been among the most successful targeted cancer therapies." (PMID 38921453, 2024). "In summary, these findings highlight the importance of detecting EGFR mutation in stage IV lung cancer patients and support the need for a personalised therapeutic approach." (PMID 39421175, 2024).
lung cancer (continued). "Recently, a tumor-promoting role of Nrp2b has been described with expression associated with lung cancer development, progression, advanced stage, worse progression-free survival, increased PD-L1 levels, and acquisition of EGFR inhibitor resistance." (PMID 38592275, 2024). "ICI treatment should be avoided in EGFR mutated lung cancer with poor PS but can be considered for lung cancer with EGFR minor mutations." (PMID 38347279, 2024). "HER2 mutations, which occur in 2% of lung cancer cases, enhance EGFR signaling, thereby promoting differentiation, proliferation, and metastasis of tumor cells." (PMID 39440051, 2024). "We are not aware of any clinical studies assessing the efficacy of either afatinib or dacomitinib in lung cancer patients presenting with EGFR extracellular domain variants." (PMID 38548752, 2024). "The upregulation of HER3 expression or signaling is associated with resistance to HER2 inhibitors in HER2-overexpressed breast cancer and to EGFR inhibitors in lung cancer; HER3 mutations have been reported as an oncogenic driver in colon and gastric cancers." (PMID 38601214, 2024). "It was reported that specific radiomic signatures from brain MRI were significantly associated with EGFR mutation status in primary lung cancer, suggesting a potential non-invasive biomarker for clinical use." (PMID 39834943, 2024). "The discovery of EGFR-activated mutations as sensitive markers for small-molecule EGFR inhibitors is not only a milestone in the history of lung cancer treatment, but also a model for personalized tumor treatment." (PMID 38674402, 2024). "Despite the challenges, osimertinib has demonstrated a well-tolerated and effective option for many patients with early-stage EGFR-mutated lung cancer." (PMID 39624538, 2024). "Non-small cell lung cancer (NSCLC) comprises over 85% of lung cancer cases, with epidermal growth factor receptor (EGFR) mutations occurring in 9–46% of NSCLC cases." (PMID 39533233, 2024). "In Taiwan, the 2-year lung cancer survival rate increased by 19.81% (95% CI 14.90%–24.71%) after the introduction of epidermal growth factor receptor (EGFR) mutations." (PMID 38974912, 2024). "EGFR is mutated in 10% of human melanoma and is an important initiator of cancer development in up to 50% of malignant glioma, lung cancer and many other cancers." (PMID 38299666, 2024). "EGFR‐mutated lung cancer patients sometimes display restricted responses to third‐generation tyrosine kinase inhibitors (TKIs), potentially attributable to undervalued input from stromal cells, notably pericytes (PCs)." (PMID 39435643, 2024). "Expression of MHC class I genes was significantly higher for lung cancers with activating mutations in EGFR." (PMID 38483480, 2024). "Literature studies concerning EGFR-TKI sensitivity in ASC harboring EGFR mutation are limited due to the low incidence of ASC in lung cancer." (PMID 39026979, 2024). "The mPFS following first-line treatment of 11 advanced patients with lung cancer-associated driver gene mutations is 26.6 months, outperforming reported outcomes of three third-generation EGFR-TKIs in the treatment of advanced LC (mPFS: 18.9–20.8 months)." (PMID 38402182, 2024). "The most common oncogenic driver mutations for non–small cell lung cancer (NSCLC) activate EGFR or KRAS." (PMID 38639476, 2024). "An example of how mutation phasing can be used in cancer treatment is in the case of epidermal growth factor receptor (EGFR) mutations in lung cancer." (PMID 38610953, 2024). "Mutations in the epidermal growth factor receptor (EGFR) gene are the most common targetable gene alterations in non‐small cell lung cancer (NSCLC)." (PMID 39245880, 2024). "We explore the genetic underpinnings of NSCLC, focusing on the role of EGFR mutations, and discuss the prevalence of early-stage lung cancer and the urgent need for timely intervention." (PMID 39624538, 2024).
lung cancer (continued). "An example of the relevance of this shift includes the increased incidence of EGFR mutations in Asian patients diagnosed with lung cancer." (PMID 38914804, 2024). "At high doses, the tested ECD variants were sensitive to the second-generation EGFR TKIs, afatinib and dacomitinib in multiple lung cancer cell lines, with particular sensitivity to dacomitinib under the tested conditions." (PMID 38548752, 2024). "Multiple studies have indicated a low prevalence of EGFR germline mutation in lung cancer, yet it has been directly associated with tumorigenesis." (PMID 39389944, 2024). "A previous report showed that cytotoxic T cells and the chemokines that recruit them are associated with the efficacy of ICIs in EGFR-mutant lung cancer, suggesting that some EGFR-lung cancers have an inflamed TME." (PMID 38347279, 2024). "This study will include all NZ patients with advanced EGFR mutation–positive lung cancer who were first dispensed erlotinib or gefitinib before October 1, 2020, and followed until death or for at least 1 year." (PMID 38954434, 2024). "Our research conclusively shows that β-elemene can counteract gefitinib resistance in lung cancer cells by suppressing autophagy linked to lncRNA H19 and halting the autophagy-driven degradation of EGFR." (PMID 38794196, 2024). "Imageomics studies predicting EGFR mutation status in patients with lung cancer typically rely on CT or MRI images of primary lung lesions." (PMID 38773634, 2024). "Exploring the clinicopathological characteristics of EGFR mutations is essential for lung cancer treatment." (PMID 39232762, 2024). "In Chinese patients, 40% of lung cancer patients have epidermal growth factor receptor (EGFR) gene mutations, compared with only 15% in European patients, and these EGFR mutations confer sensitivity to tyrosine kinase inhibitors (TKIs)." (PMID 38803532, 2024). "The molecular characterization of lung cancer has led to the identification of novel biomarkers, such as epidermal growth factor receptor mutations and anaplastic lymphoma kinase translocations, which are essential for targeted molecular therapies." (PMID 39195131, 2024). "Nevertheless, the efficacy of osimertinib in EGFR ex20ins mutations in lung cancer remains controversial." (PMID 38774882, 2024). "scRNA-seq of EGFR-mutated lung cancer cell lines captures changes in apoptosis-related gene expression following EGFR-TKI treatment, most notably BCL2L1 upregulation." (PMID 39122703, 2024). "This study aims to evaluate the value of the quantitative metabolic parameters derived from dynamic FDG PET/CT in the differential diagnosis of lung cancer and predicting epidermal growth factor receptor (EGFR) mutation status." (PMID 38730287, 2024). "PARP4 depletion or mutation (I1039T) promotes the tumorigenicity of KRAS- or EGFR-driven lung cancer cells." (PMID 39034402, 2024). "Epidemiological data from the International League of Lung Cancer showed that EGFR mutations accounted for 35.0% of 4231 NSCLC patients who underwent epidermal growth factor receptor (EGFR) gene testing." (PMID 39070151, 2024). "EGFR ex20ins, as the third most common EGFR mutation, holds a significant place within the broad spectrum of lung cancer patients." (PMID 38919530, 2024). "EGFR mutation was detected in 3/50 (6%) of lung cancer cases, and all the cases with EGFR mutation revealed exon 19 deletion." (PMID 39205175, 2024). "Lung cancer patients with mutations in the epidermal growth factor receptor (EGFR) gene are often treated with drugs called EGFR tyrosine kinase inhibitors (EGFR-TKIs)." (PMID 39682169, 2024). "Choroidal metastasis appeared in a patient with lung cancer with an EGFR L858R mutation during treatment with the first-generation EGFR-TKI, gefitinib." (PMID 38962043, 2024).
lung cancer (continued). "This combined method shows promise as a successful treatment option for patients with glioblastoma and lung cancer with various EGFR mutations, including those who have developed resistance to osimertinib in Non-Small Cell Lung Cancer (NSCLC)." (PMID 38512527, 2024). "The 2018 CAP/AMP/IASLC (College of American Pathologists/Association of Molecular Pathology/International Association for the Study of Lung Cancer) guidelines advocated testing for EGFR, ALK, ROS1, and BRAF upfront." (PMID 39834530, 2024). "For example, loss of phosphatase and tensin homolog (PTEN) expression in lung cancer cells leads to resistance to the TKI erlotinib by activating EGFR and Akt kinases." (PMID 38877005, 2024). "For instance, Roche cobas and Biocartis Idylla’s lung cancer epidermal growth factor receptor (EGFR) mutation tests both use 2 mL of blood plasma as a specimen." (PMID 39858690, 2024). "When lung cancer is found to be mutated in the epidermal growth factor receptor (EGFR), targeted drugs of the tyrosine kinase inhibitor (TKI) family have proven to be successful treatment options." (PMID 39202551, 2024). "On the other hand, several studies found the rare germline T790M mutation in EGFR correlated with the familial clustering of lung cancer." (PMID 39199663, 2024). "Patients with NSCLC with EGFR exon 20 insertions exhibit similar clinical characteristics (e.g., age, smoking status, lung cancer subtype) to patients carrying common EGFR mutations." (PMID 39190099, 2024). "The activation of EGFR signaling was linked to various cancer development, such as lung cancer and glioma, through its downstream signaling crosstalk with the MAPK, Akt, STAT3 and PKC signaling pathways." (PMID 39451518, 2024). "MET amplification is a common determinant of acquired resistance to EGFR-TKI among lung cancer patients harboring EGFR mutations." (PMID 38566036, 2024). "A particular focus will be on determining epidermal growth factor receptor (EGFR) mutations in lung cancer, which currently serves as a concrete example of an optimized, targeted therapy approach in a specific tumoral localization." (PMID 39337479, 2024). "Lung cancers with classic EGFR mutations, such as exon 19 deletion (ex19del) and the exon 21 p.Leu858Arg (L858R) point mutation, are responsive to first-to-third-generation EGFR-TKIs, including gefitinib, erlotinib, afatinib, and osimertinib." (PMID 38687753, 2024). "Currently, EGFR expression is significantly associated with PD-L1 and has now been demonstrated to be an independent factor in regulating PD-L1 protein in lung cancer." (PMID 38972967, 2024). "Studies have shown a direct relationship between acquired EGFR mutations and drug resistance in lung cancer patients treated with EGFR‐TKIs." (PMID 38584122, 2024). "Univariate and multivariate analyses were performed in 67 patients to assess the clinical factors associated with TTNT for immunotherapy in EGFR-mutant lung cancer." (PMID 38347279, 2024). "An established first-line therapy for EGFR-mutated lung cancer cases with distant metastasis is administration of an EGFR tyrosine kinase inhibitor (TKI)." (PMID 38898314, 2024). "It initially received FDA approval in 2014 for the treatment of metastatic gastric cancer in the second line setting and most recently received FDA approval in 2020 for the first‐line treatment of metastatic EGFR‐mutated non‐small cell lung cancer." (PMID 38698690, 2024). "We can note that in a retrospective cohort study of 239 patients, an SRT approach led to an OS improvement compared to a WBRT approach in a population of patients presenting metastatic EGFR-mutated lung cancer with BM (HR = 0.38, 95% CI 0.17–0.84, p = 0.017)." (PMID 38730695, 2024).
lung cancer (continued). "Epidemiological analyses of germline H988P allele prevalence among EGFR-mutant lung cancers in the African American population should be undertaken, and the allele should be considered as having uncertain clinical relevance until then." (PMID 39406916, 2024). "For instance, epidermal growth factor receptor (EGFR), ranked as the top 1 in the prediction results, has been found to be associated with certain lung cancers." (PMID 39392404, 2024). "First‐line osimertinib plus chemotherapy significantly prolonged progression‐free survival of patients with EGFR‐mutated advanced non‐small cell lung cancer (NSCLC) compared to osimertinib, according to the FLAURA2 trial." (PMID 39206619, 2024). "The real-world data presented here support the translation of results from clinical trials to routine clinical care for targeted therapy in EGFR mutated lung cancer but also highlight the need for clinical trials that are more inclusive." (PMID 38539415, 2024). "This mutation also contributes to resistance to EGFR-TKIs in lung cancer by activating downstream effectors such as AKT and mTOR." (PMID 39743996, 2024). "Tissue biopsy is considered as the gold standard for EGFR variant test in lung cancer, mainly for NSCLC." (PMID 38245692, 2024). "Lung cancer (NSCLC) with a specific genetic mutation (EGFR ex20ins) that has worsened despite receiving platinum-based chemotherapy." (PMID 38910714, 2024). "This study explored biomarkers of adjuvant therapy for resected epidermal growth factor receptor (EGFR)‐mutated non‐small cell lung cancer using tumor specimens from the phase III IMPACT study." (PMID 37864465, 2024). "Mutations in the epidermal growth factor receptor (EGFR) are often correlated with cancer therapy tolerance in lung cancer." (PMID 38418707, 2024). "Hypopharyngeal cancer is a type of head and neck cancer and EGFR‐mutated lung adenocarcinoma is also one form of lung cancer." (PMID 38783639, 2024). "According to previous studies, features extracted from CT images of lung cancer patients are associated with gene expression patterns and can be utilized to predict EGFR mutation profiles." (PMID 38195717, 2024). "The first cited reference is the EGFR mutations in lung cancer: Correlation with clinical response to gefitinib therapy written by PAEZ JG." (PMID 39872524, 2024). "In certain case, a correlation has been explored between EGFR mutation and the metastasis of lung cancer to the breast." (PMID 39193383, 2024). "The deletion in exon 19 of the EGFR gene is one of the most detected mutations in lung cancer patients." (PMID 38730722, 2024). "The epidermal growth factor receptor (EGFR) driver gene is mutated in approximately one-third of lung cancer patients." (PMID 38957318, 2024). "Our study revealed a significant association between age over 50 years and EGFR mutations in primary lung cancers." (PMID 39429333, 2024). "Future pre-clinical and possibly clinical studies will be needed to assess the use of dacomitinib or other EGFR TKI’s as a treatment strategy for lung cancer patients, and potentially glioblastoma patients, whose cancers harbor EGFR ECD variants." (PMID 38548752, 2024). "Determining the exact type of epidermal growth factor receptor (EGFR) exon 20 insertion (ex20ins) mutation in lung cancer has become important." (PMID 38687753, 2024). "We also explored acquired resistance mechanisms to front-line 4G EGFR-TKI exposure using lung cancer cell lines with activating EGFR mutation." (PMID 39061985, 2024). "Cohort studies have demonstrated that GERD is a significant risk factor for EGFR-mutant lung cancer, and acid bile salt mimics GERD exposure and enhances ERBB2-mediated activation of immune cell/inflammatory pathways." (PMID 38414734, 2024).